CD40 (CD40 molecule)
Diseases named in the same sentence as CD40 in open-access papers (continued):
Sharing a sentence is not in itself a finding about the gene and the disease.
Autoimmunity (64 papers, 2006 to 2026). The occurrence of an immune reaction against the organism's own cells or tissues. "In the context of autoimmunity, upregulated CD40 signaling has been implicated in sustaining aberrant immune responses and driving chronic inflammation." (PMID 41403945, 2025). "Uncontrolled activation of CD40L/CD40 results in autoimmune disorders and the biological processes associated with organ transplant rejection." (PMID 39480764, 2024). "We extracted genomic DNA from the whole blood of 13 GD patients treated with Iscalimab, and genotyped seven CD40 single nucleotide polymorphisms (SNPs) associated with autoimmunity." (PMID 34149627, 2021). "We suggest that γHV-68 latency, in concert with the increase in CD40 expression on APCs, drives a decrease in Treg frequencies and thereby increases susceptibility to autoimmunity." (PMID 26356194, 2015). "In fact, we determined that an intricate balance between Tregs and potentially pathogenic Th40 cells must be maintained to prevent autoimmunity and this process is tightly associated with CD40 signaling." (PMID 18446238, 2008). "Equally, excessive IL‐21 production could result in the potentially detrimental lowering of BCR or CD40 signaling thresholds and/or exaggerated B cell expansion and thus predispose to autoimmunity." (PMID 35801309, 2022). "The CD40 rs1883832 was shown to have a substantial association with some form of autoimmunity." (PMID 36451826, 2022). "Given the pivotal role of CD40 in the development of GD and autoimmunity, reduced CD40 expression induced by rs1883832 may decrease the risk of developing GD." (PMID 30956635, 2019). "In our work, by using cell-type-specific targeting approaches, we have shown that miR-146a controls GC reactions primarily through regulating the CD40 signaling pathway in GC B cells and that loss of miR-146a in B cells is sufficient to lead to the development of spontaneous autoimmunity." (PMID 30013024, 2018). "Accordingly, CD40 may be contributing to an inflammatory state following infection that leads to autoimmunity and can potentially be used as a biomarker for pathogenic T cells." (PMID 28974943, 2017). "Determination of whether other viruses positively associated with T1D onset may be eliciting CD40-expressing immune cells could be important for understanding how these environmental pathogens are promoting development of autoimmunity." (PMID 28974943, 2017). "Given the pivotal role of regulatory B cells in the control of autoimmunity, our findings may provide novel mechanism of autoimmune pathogenesis via LPS-associated suppression of CD40-activated regulatory B cells." (PMID 26236564, 2015). "The important role of the CD40-CD40LG pathway in autoimmunity, together with the association of the CD40 gene with a number of autoimmune diseases, prompted us to investigate for the first time the contribution of CD40 and CD40LG genes in SSc." (PMID 22731751, 2012). "Therefore, we hypothesized that one of these autoimmunity associated CD40 SNPs, or a haplotype consisting of a combination of them, may play a role in the clinical response of GD patients to Iscalimab." (PMID 34149627, 2021). "Therefore, it is tempting to speculate that loss of miR-146a-mediated CD40 regulation in B cells could also play an important pathogenic role in contributing to this complex autoimmune disorder." (PMID 30013024, 2018). "It is possible that certain defects in the glycosylation machinery would obligatorily lead to autoimmunity but in a situation where glycosylation processes are intact, excessive CD40 signaling could cause immune activating changes in glycosylation status and then lead to autoimmunity." (PMID 22685601, 2012). "Therefore, constitutive, robust CD40 signals may drive functional B10pro cell expansion and limit the pathogenic consequences of autoimmunity by reducing Ab isotype switching." (PMID 21799861, 2011).
Autoimmunity (continued). "The interaction of CD40L and its receptor CD40 on activated T cells and B cells respectively control pro-inflammatory activation in the pathophysiology of autoimmunity and transplant rejection." (PMID 39480764, 2024). "Dendritic cell CD40 upregulation following TLR9 ligand mediated activation was identified as a critical second signal for the induction of nephritogenic autoimmunity." (PMID 36674855, 2023). "Both anti CD154 and anti CD40 antibodies have progressed into clinical development programs in autoimmunity and solid organ transplant." (PMID 35464470, 2022). "Other studies reported that DT-mediated depletion of Foxp3+ cells in DEREG mice induced increased division of DC and precursor DC in lymphoid organs and up-regulation of CD80, CD86 and CD40 in the context of autoimmunity." (PMID 36846549, 2022). "For example, while loss-of-function mutations in CD154 (TNFSF5) and CD40 (TNFRSF5) are linked to immunodeficiencies in mice and humans, gain-of-function alterations are associated with autoimmunity and B cell malignancy." (PMID 34813503, 2022). "They proposed CD40 overexpression on thyrocytes augmented thyroid-directed autoimmunity through two possible mechanisms." (PMID 34867801, 2021). "Anti-CD40 monoclonal antibodies (mAbs) comprise agonists and antagonists, which display promising therapeutic activities in cancer and autoimmunity, respectively." (PMID 32442402, 2020). "Whereas, this study indicates that a normalized BCR signal could restore immune tolerance, the strong role of CD40 activation in PTPN22 risk gene carriers is also consistent with the idea that this pathway is critical for censoring the overly active immune system in autoimmunity." (PMID 31616406, 2019). "As with other Breg subsets, the suppressive function of B10 cells depend on CD40 engagement and several experimental mouse models have proven the efficacy of B10 cells in dampening autoimmunity." (PMID 31120872, 2019). "Anti-CD40 monoclonal antibodies (mAbs) that promote or inhibit receptor function hold promise as therapeutics for cancer and autoimmunity." (PMID 29576376, 2018). "So, outside of the systemic immune compartment CD40 increases organ-specific autoimmunity and within the CNS CD40 expressing cells regulate the EAE development in BM chimeric mice." (PMID 29312317, 2017). "IL-2 promotes Tregs and knockout of IL-2 or IL-2-receptor causes lethal autoimmunity, therefore CD28 drives a more regulatory environment while CD40 promotes an inflammatory environment." (PMID 28192476, 2017). "Our results also suggest that agonistic anti-CD40 antibodies should be used with caution, since they can promote autoimmunity, particularly if a target organ such as the thyroid expresses CD40." (PMID 25400914, 2013). "In autoimmunity the major focus has been on signaling outcomes, associated signaling molecules, and on preventing its ligand, CD154, from signaling through CD40." (PMID 22685601, 2012). "While it has long been understood that CD40 plays a critical role in the etiology of autoimmunity, glycobiology is emerging as an important contributor." (PMID 22685601, 2012). "T and B cell CD154 expression in SLE patients is proposed to drive autoimmunity, and a clear role for aberrant CD40 signaling in other inflammatory autoimmune diseases has emerged in recent years." (PMID 21799861, 2011). "B cell regulatory functions are also enhanced by ex vivo CD40 or LPS stimulation in inflammation and autoimmunity models, although CD40 or TLR signaling are not required for B10pro or B10 cell generation." (PMID 21799861, 2011). "In order to explore the protective effect of CD40 siRNA for potential clinical use, we treated mice at the stage of post-initiation of the autoimmunity." (PMID 20102615, 2010). "In autoimmunity there is an expansion of a CD40-expressing T cell subset that also is characterized by its low surface-expression of CD4." (PMID 18446238, 2008).
Autoimmunity (continued). "These intrinsic differences relative to CD40, and now Fas, signaling suggest a mechanism to promote autoimmunity." (PMID 18446238, 2008). "On the other hand, enhanced CD40 signaling through TRAF3 mutations led to autoimmunity and increased risk of B-cell malignancy in humans, while a lack of CD40 signaling through CD40L mutations led to immunodeficiency in humans." (PMID 40473841, 2025). "On one hand, CD40 could present antigen and deliver costimulatory signals to T cells and induce the activation of T cells and ultimately enhancing the autoimmunity." (PMID 38586452, 2024). "CD40 upregulation by TLR9 was critical for the induction of nephritogenic autoimmunity." (PMID 36674855, 2023). "CD40 is a critical second signal for the induction of anti-MPO autoimmunity." (PMID 36674855, 2023). "CD40 upregulation is shown to be a critical second signal to induce nephritogenic autoimmunity." (PMID 36674855, 2023). "Addressing these questions may allow us to develop new strategies to rescue defective antibody responses in CD40-deficient mouse model or human PID patients, and to better treat autoimmunity or B cell lymphoma by modulating BCR signaling pathways." (PMID 33841447, 2021). "In this study, we examined the in vitro effects of KPL-404, a humanized anti-CD40 monoclonal antibody (Ab), on primary human B cells derived from either healthy donors (HD) or autoimmune patients and compared them to the effects of G28-5, a partially antagonistic anti-CD40 antibody." (PMID 33407802, 2021). "The intrinsic mechanism, through the activation of CD40 signaling pathway within the thyrocytes could alter their physiology, lead to inflammation and autoimmunity." (PMID 34867801, 2021). "It has been reported that B10 cells induced by CD40 mAb10 or CpG19 inhibited arthritis in animal models, suggesting that in vitro induced Bregs could be applied for the treatment of autoimmunity disease." (PMID 34099635, 2021). "Based on these findings, we propose that while Act1 is a necessary signaling molecule for IL-17 signaling, Act1 serves as a negative regulator to modulate Th17-B cell interaction via its impact on IL-23/IL-21/STAT3 axis and CD40, thereby controlling autoimmunity." (PMID 30013031, 2018). "In this model of EAM induction by BMDCs, initial autoimmunity was induced by repeated immunization with CD40 and LPS-matured BMDCs, yet subsequently, cardiac endogenous cDC2s acquired a capacity to present cardiac self-antigen ex vivo, a feature not seen with cDC2s isolated from steady state hearts." (PMID 30524444, 2018). "CD40 on peripheral hematopoietic cells is known to be pivotal to the development of autoimmunity." (PMID 29312317, 2017). "CD40, a glycoprotein belonging to the tumor necrosis factor receptor superfamily, is a costimulatory protein that is expressed on APCs, including dendritic cells, activated macrophages, and mature B cells, and contributes to autoimmunity." (PMID 29073149, 2017). "CD40 signaling leads to isotype switching and autoantibody production in B cells and in T-cell priming, altering TCR expression through the expression and nuclear translocation of recombinases, which increases the risk of developing autoimmunity." (PMID 23533546, 2013). "Controlling CD40 signaling has long been an elusive goal in autoimmunity." (PMID 22685601, 2012). "This could be due to the high availability of CD154 in autoimmunity that can constantly engage CD40 on these T cells." (PMID 18446238, 2008). "Therefore it is possible that CD40, via cFLIPp43, acts as a switch between Fas-induced cell death and survival/proliferation of these cells in autoimmunity." (PMID 18446238, 2008). "However, the present data demonstrate that conditions prevailing in autoimmunity lead to hyperexpression of CD40 on the potentially autoaggressive Th40 cell subset." (PMID 18446238, 2008).
Autoimmunity (continued). "CD40 is a member of the TNF receptor (TNFR) family, whose expression in macrophages has been associated with pathologic conditions, and IL-6 has been described as a crucial pleiotropic pro-inflammatory cytokine that regulates inflammation during cancer, autoimmunity, and infectious diseases." (PMID 35745755, 2022). "Therefore, apoptosis was induced in the presence of anti-CD40 and/or CpG DNA to determine whether this would alter the fate of T cells and lead to enhanced T cell function and autoimmunity." (PMID 28257518, 2017). "Since CTLA4-Ig mediated co-stimulatory blockade induces remission of autoimmunity, we sought to determine whether a temporary suppression of CD40 expression by administration of siRNA may induce immune modulatory effects on RA that predispose towards reduction of immunity towards the autoantigen." (PMID 20102615, 2010). "Additionally, it indicates that the CD40-signaling pathway that leads to cFLIPp43 expression could be targeted to control the Th40 cells in autoimmunity." (PMID 18446238, 2008). "TLR9 ligation enhanced dendritic cell activation upregulating CD40 and CD80 expression, promoting systemic anti-MPO autoimmunity and T cell recall responses and exacerbating kidney injury." (PMID 36674855, 2023). "It has long been understood that CD40 – CD154 interactions are critical in the etiology and perpetuation of autoimmunity and CD40 is gaining further interest in cancer and tissue transplantation therapies." (PMID 22685601, 2012). "CD40−/− dendritic cells were generated; these cells were pulsed with MPO and stimulated with the TLR9 ligand and their ability to induce nephritogenic autoimmunity when transferred to naïve wild type mice was compared to TLR9 stimulated MPO pulsed WT dendritic cells." (PMID 36674855, 2023). "It remains to be understood whether alterations in the required rewiring of the PI3K signaling network downstream of CD40 and the BCR and dynamic activity of mTORC1 is disturbing selection and thereby contributes to the observed autoimmunity in these patients." (PMID 35159274, 2022). "Many studies have reported aberrant CD40 signaling in patients with autoimmune diseases, which supports the notion that the CD40-CD40L interaction contributes to B-cell hyperactivation and the maintenance of autoimmunity." (PMID 36220996, 2022). "These previous data were, however, mainly acquired in the context of autoimmunity, where B cells receive a multitude of different signals and IFNγ signaling seems primarily to synergize with BCR-, CD40- and TLR-mediated stimuli to induce spontaneous germinal centers." (PMID 35187121, 2022). "The CD40/CD40L pathway is central to both cellular and humoral adaptive immunity with implications for effective tumor surveillance/control, immune homeostasis, and autoimmunity." (PMID 32442402, 2020). "A greater understanding of the dynamics of CD40 and CD3 signaling and the impact of the availability of those molecules for signaling on the surface of the cells will be imperative in understanding how to control those cells in autoimmunity." (PMID 22685601, 2012). "The expansion of CD4loCD40+ T cells in autoimmunity, their often low surface expression of CD3 and the constant signaling through CD40 on those cells indicates that autoimmune mouse CD4loCD40+ T cells may not be able to readily receive CD3 signals." (PMID 22685601, 2012). "Furthermore, BCR signaling regulates BAFFR levels, and BAFF supports CD40 expression and T cell costimulation through BAFFR, suggesting the presence of a self-amplifying loop that supports the survival of self-reactive B cells in autoimmunity." (PMID 36359789, 2022). "The recent discovery that the CD40 co-stimulatory molecule is expressed on T cells, not only APCs as previously thought, led to the hypothesis that CD40+CD4+ T cells, termed by Wagner as Th40 cells, could contribute to pathogenesis in autoimmunity." (PMID 28974943, 2017).
Autoimmunity (continued). "Genetic linkage studies do not indicate CD40 as a candidate gene in autoimmunity." (PMID 18446238, 2008). "Another antagonistic anti-CD40 Ab CFZ533, which is being evaluated for treatment of autoimmune patients, was shown to internalize upon its binding to CD40, suggesting that Ab internalization alone does not determine whether it will have agonistic or antagonistic properties." (PMID 33407802, 2021). "The interaction of CD40 and CD154 has been shown to be involved in the negative regulation of T cell autoreactivity and abnormalities in their interaction may lead to autoimmunity." (PMID 31357536, 2019). "The interaction of CD40 and CD40L has been shown to be involved in the negative regulation of T cell autoreactivity and abnormalities in their interaction may lead to autoimmunity." (PMID 21297967, 2011). "In a recent study, CD19+CD24hiCD38hi Bregs from patients with SLE were found to be refractory to CD40 engagement and produced less IL-10 and lacked CD4+ T-cell suppressive capacity compared with the healthy controls, suggesting that functional defects of Bregs could lead to autoimmunity." (PMID 26209442, 2015).